MEG3 (maternally expressed 3)
Diseases named in the same sentence as MEG3 in open-access papers (continued):
Sharing a sentence is not in itself a finding about the gene and the disease.
ovarian carcinoma (continued). "MEG3 expression is significantly reduced in ovarian cancer tissue compared to normal ovarian tissue, and its overexpression causes inhibition of growth and proliferation and induces apoptosis in the OVCAR3 ovarian cancer cell line." (PMID 28637507, 2017). "However, miR-26a has been shown to promote proliferation and tumorigenesis of ovarian cancer cells through the targeting of ER-α, suggesting a putative different relationship between MEG3 and miR-26a in ovarian cancer that remains to be investigated." (PMID 26992233, 2016). "Finally, we also validated the inhibitory effect of MEG3 on ovarian cancer in a xenograft model." (PMID 38281945, 2024). "We demonstrated that MEG3 could inhibit the proliferation and migration of ovarian cancer cells." (PMID 38281945, 2024). "As such, whether MEG3 functions as a tumor suppressor in ovarian cancer remains to be determined." (PMID 34069546, 2021). "However, little is known regarding the role of Meg3 in epithelial ovarian cancer (EOC)." (PMID 28423647, 2017). "Consequently, it has been deduced that MEG3 promoter hypermethylation may contribute to the development of epithelial ovarian cancer." (PMID 27664137, 2017). "In ovarian cancer, several lncRNAs like HAND2-AS1, HOXA11-AS, and HOTAIRM1 demonstrate tumor-suppressive roles similar to MEG3." (PMID 40242248, 2025). "In ovarian cancer, GAS5 disrupts mitochondrial membrane potential and influences apoptosis pathways, similarly to MEG3, through the promotion of BAX, BAK, and caspases." (PMID 40242248, 2025). "XIST, MEG3, IPW, HAND2‐AS, ADAMTS9‐AS2, and LINC00312 have been reported to be downregulated in ovarian cancers in several studies, which is consistent with the present study." (PMID 38571514, 2024). "Overexpression of MEG3 suppressed the degradation of VASH1 by negatively regulating miR-885-5p, inhibiting the ovarian cancer malignant phenotype." (PMID 38281945, 2024). "We demonstrated that MEG3 is influenced by METTL3/YTHDF2 methylation and restrains ovarian cancer proliferation and metastasis by binding miR-885-5p to increase VASH1 expression." (PMID 38281945, 2024). "In this study, we constructed the lncRNA-mediated ceRNA networks to reveal that miR-320b and miR-320d were probably involved in the mechanisms of platinum resistance in ovarian cancer patients mediated by SNHG12, MEG3, and NR2F1-AS1." (PMID 35592674, 2022). "One study showed that lncRNA PVT1 was elevated in cisplatin resistant ovarian cancer tissues, while lncRNAs TUG1 and MEG3 were decreased in ovarian cancer patients with cisplatin resistance." (PMID 36105363, 2022). "It has been reported that both MEG3 and PTEN are downregulated in ovarian cancer cells, which promotes tumor cell proliferation and inhibits cell apoptosis." (PMID 36523500, 2022). "Here, we aimed at elucidating the clinical relevance of MEG3 in a homogenous series of advanced HGSOC patients; then, we investigated its function in ovarian cancer biology." (PMID 32295169, 2020). "In epithelial ovarian cancer (EOC), the MEG3 overexpression inhibited tumorigenesis by increasing early-stage cell apoptosis in a xenograft mouse model." (PMID 32489317, 2020). "To investigate the action of Meg3 in EOC, we analyzed the mRNA expression of Meg3 in normal epithelial ovarian tissues, benign tumor tissues, primary ovarian carcinomas, and metastatic omentum tumors." (PMID 28423647, 2017). "After transfecting the ovarian cancer cell lines OVCAR3 and A2780 with Meg3, phenotypic changes and autophagy-related molecules were examined." (PMID 28423647, 2017). "Here we report an integrated analysis of >700 ovarian cancer molecular profiles, including genomic data sets, from four patient cohorts identifying lncRNA DNM3OS, MEG3, and MIAT overexpression and their reproducible gene regulation in ovarian cancer EMT." (PMID 29150601, 2017).
ovarian carcinoma (continued). "In this study, we comprehensively demonstrated that lncRNA MEG3 is regulated by METTL3-mediated YTHDF2 methylation; it upregulates VASH1 through regulatory competitive binding to hsa-miR-885-5p and then inhibits ovarian cancer cell proliferation, migration, and invasion." (PMID 38281945, 2024). "The expression levels of MEG3 in ovarian cancer cell lines (A2780, OVCAR3, Caov3, and SKOV3) and ovarian normal epithelial cells were verified by PCR." (PMID 38281945, 2024). "In addition, MEG3 has been confirmed to target hsa-miR-885-5p, thereby upregulating the expression of VASH1 and exerting an inhibitory effect on ovarian cancer." (PMID 38281945, 2024). "Recently, in our laboratory, four aberrantly expressed lncRNAs (MEG3, POU5F1P5, ADAMTS9‐AS2, and XIST) were identified in ovarian cancer cell lines and primary ovarian surface epithelial cells and subsequently validated using multiple HGSCs and ovarian tissues." (PMID 38571514, 2024). "It appears that there is a reciprocal regulation of miR-421 and MEG3, as the forced expression of MEG3 inhibits the level of miR-421 in OCSCs, and overexpression of miR-421 results in a reduction in MEG3 and platelet-derived growth factor receptor A (PDGFRA) in ovarian cancer stem cells." (PMID 34069546, 2021). "The Meg3 promoter was reported to be methylated and MEG3 expression was absent or reduced in ovarian cancer tissues and cell lines." (PMID 26992233, 2016). "Systematic mapping of lncRNA networks under these treatment conditions could reveal a hierarchy of non-coding RNAs that collectively govern ovarian cancer behavior, with MEG3 occupying a central but not solitary position." (PMID 41480643, 2026). "From lncRNA expression profiling of extracellular vesicles purified from ovarian cancer A2780 cells cultured with and without the curcumin, they showed changes in the expression of a large number of lncRNAs, being MEG3 one of the most upregulated due to demethylation in its promoter region." (PMID 34204094, 2021). "However, research on MEG3 in ovarian cancer is not yet abundant or fully investigated." (PMID 38281945, 2024).
osteosarcoma (45 papers, 2012 to 2025). A usually aggressive malignant bone-forming mesenchymal neoplasm, predominantly affecting adolescents and young adults. "The downregulation of lncRNA MEG3 was noted in patients with osteosarcoma and was associated with tumour progression and metastasis." (PMID 36139691, 2022). "The results confirmed the molecular phenotype of the osteosarcoma cells, associated with their invasiveness and manifested by low expression of MEG3 and high mRNA levels for metalloproteinases, especially for MMP-14." (PMID 36139691, 2022). "A microRNA (miRNA) collection on the imprinted 14q32 MEG3 region has been associated with outcome in osteosarcoma." (PMID 28506242, 2017). "Consequently, decreased expression of MEG3 in human osteosarcoma tissue is associated with advanced clinical stage (I/II vs. III) and presence of distant metastasis." (PMID 29657304, 2018). "Osteosarcoma studies indicate that downregulation of MEG3 enhances miR-184 activity, promoting proliferation and metastasis." (PMID 41379397, 2025). "The EVs were isolated from MSCs that have been transfected with MEG3 and these EVs were then used to inhibit osteosarcoma cell growth." (PMID 40176023, 2025). "MEG3 was reported to downregulate miR-184 in osteosarcoma cells, resulting in reduced proliferation and migration, and increased apoptosis." (PMID 41379397, 2025). "MiR-184, as well as β-catenin, TCF4, and c-MYC, which are downstream Wnt signaling pathway factors, is negatively impacted by MEG3, which inhibits the replication and the migration of osteosarcoma cells in vitro and cancerous growth in vivo." (PMID 39015175, 2024). "Other studies have shown that MEG3 negatively regulates the proliferation, migration, and apoptosis of osteosarcoma through the Wnt/β-catenin pathway by targeting miR-184." (PMID 38827318, 2024). "In patients presenting with osteosarcomas, low levels of MEG3 expression, a late pathological stage, and the presence of remote tumor deposits were all determined to be autonomous markers of reduced overall survival time." (PMID 39015175, 2024). "When contrasted with neighboring benign tissue samples, there was an obviously reduced MEG3 expression in tissues from osteosarcomas." (PMID 39015175, 2024). "on osteosarcoma, researchers coupled Exo-MEG3 with a tumor-targeting cRGD peptide, which demonstrated precise tumor-targeting ability and enhanced anti-tumor effects in an osteosarcoma model." (PMID 38595822, 2024). "Long-noncoding RNA Maternally Expressed Gene 3 (lncRNA MEG3), which functions as a sponge for miRNAs, is under-expressed in osteosarcoma tissues." (PMID 37894887, 2023). "LncRNA MEG3 is underexpressed in several human malignancies, including non-small-cell lung cancer, colorectal cancer, and osteosarcoma." (PMID 37190068, 2023). "Researchers loaded EVs engineered to target the αvβ3 integrin through the engineered expression of the cRGD peptide with lncRNA MEG3, and they successfully targeted osteosarcoma cells in vivo." (PMID 37894887, 2023). "As a result, the advanced clinical stage (I/II vs. III) and the existence of distant metastasis are related to lower MEG3 expression in human osteosarcoma tissue." (PMID 37190068, 2023). "Two years ago, a team from Nanjing medical university stated that MEG3 contributes greatly to the diagnosis and treatment of osteosarcoma by sponging miRNAs." (PMID 36544907, 2022). "MEG3 and miR-361-5p regulate FoxM1 in vitro and inhibit the proliferation, migration and invasion of osteosarcoma cells." (PMID 36523500, 2022). "Emerging evidence reported that MEG3 knockdown was an independent prognostic biomarker affecting the OS of patients with osteosarcoma." (PMID 36544907, 2022). "For example, lncRNA MEG3 was combined with exosome through engineering technology and used to treat osteosarcoma animal models." (PMID 35898869, 2022). "The results of miR-664a inhibition assay showed that up-regulation of miR-664a inhibits MEG3 gene expression in osteosarcoma." (PMID 36544907, 2022).
osteosarcoma (continued). "To facilitate the detection of MEG3 lncRNA in living cells, we generated an osteosarcoma U2OS cell line in which an inducible MEG3 gene was stably expressed." (PMID 35741072, 2022). "We developed U2OS osteosarcoma cell clones containing a doxycycline-inducible MEG3 (U2OS-MEG3) and confirmed that MEG3 was induced 100 to 200-fold on doxycycline treatment as determined by qRT-PCR." (PMID 33722609, 2021). "Forced expression of MEG3 hindered osteosarcoma cell proliferation and migration in vitro, and retarded tumor growth in vivo." (PMID 34130697, 2021). "It is regulated by lncRNA Ewing-sarcoma associated transcript-1 (EWSAT1) and downregulation of MEG3 in the presence of EWSAT1 leads to proliferation, invasion, and cellular migration of osteosarcoma cells, based on gain- and loss-of-function assays." (PMID 29657304, 2018). "The lncRNA Maternally expressed gene 3 (MEG3) is under-expressed in several human cancers, including non-small cell lung cancer, colorectal cancer and osteosarcoma." (PMID 29657304, 2018). "The altered lncRNA expression profile possessed a total of 9 individuals, yet 7 of them (TUG1, 91H, HULC, BANCR, FGFR3-AS1, HOTTIP, and OMRUL) were overexpressed in osteosarcoma tissues/plasma, and 2 (MEG3 and TUSC7) were down-regulated." (PMID 28415638, 2017). "On the other hand, abundance of two types of lncRNAs, MEG3 and TUSC7 were demonstrated to be down-regulated in osteosarcoma patients and significantly associated with survival times." (PMID 28415638, 2017). "Multivariate analysis indicated the expression of MEG3 to be one independent predictor of overall survival in osteosarcoma patients." (PMID 28353666, 2017). "For instance, lncRNA–miRNA axes such as MEG3/miR-664a and TUG1/miR-144-3p have been mechanistically linked to OS progression; knockdown of the oncogene lncRNA NEAT1 restores the availability of miR-34c and delays the tumor growth in osteosarcoma." (PMID 41331461, 2025). "For example, long non-coding RNA MEG3 was used in EV-based therapy for osteosarcoma cells." (PMID 40176023, 2025). "The results showed that cRGD-Exo-MEG3 could deliver MEG3 to osteosarcoma cells more effectively than unmodified exosomes and equip significant anti-osteosarcoma effect." (PMID 37351470, 2023). "Another study observed that the MEG3/miR-644a axis may be a novel factor for the diagnosis and treatment of osteosarcoma." (PMID 36544907, 2022). "Finally, very recent research showed that tumor-targeting therapy of osteosarcoma (OS) can be performed by a highly effective engineered and MEG3-loaded exosome, as a combination of MEG3 and exosome significantly increased MEG3 therapeutic effect." (PMID 36551518, 2022). "The results showed that compared to the MEG3 group, the cRGD-modified exosomes emitted stronger fluorescence signals in the tumor site, confirming that the cRGD-modified exosomes had a stronger ability to target lncRNA delivery to osteosarcoma." (PMID 36726721, 2022). "Our study confirmed decreased expression of MEG3 in the osteosarcoma cell lines." (PMID 36139691, 2022). "A recent study reported that MEG3 was aberrantly expressed in osteosarcoma." (PMID 34130697, 2021). "Additionally, several lncRNAs are downregulated in osteosarcoma with potential tumor-suppressive activity such as loc285194, MEG3, and TUSC7." (PMID 31616462, 2019). "In addition, the expression pattern of miRNAs in the MEG3 region can also identify previously unrecognized distinct molecular subtypes of osteosarcoma." (PMID 29069869, 2017). "Furthermore, decreased MEG3 lncRNA expression, advanced clinical stage, and distant metastasis were all independent predictors of shorter overall survival in osteosarcoma patients." (PMID 27685633, 2016).
osteosarcoma (continued). "In addition, another research group demonstrated that MEG3 might inhibit the development and metastasis of osteosarcoma by inhibiting the Notch and TGFβ signaling pathways." (PMID 36544907, 2022). "Not long after, another team confirmed that the MEG3/miR-361-5p/forkhead box M1 (FoxM1) signaling axis may be a diagnostic biomarker or therapeutic target for osteosarcoma." (PMID 36544907, 2022). "Moreover, the inhibitory effect of MEG3 could be reversed by miR-184 mimic, suggesting a cooperative regulation of MEG3 and miR-184 in osteosarcoma." (PMID 34130697, 2021). "Moreover, low MEG3-levels correlate with poor overall survival (OS) in osteosarcoma patients." (PMID 29657304, 2018). "Therefore, MEG3 could serve as a prognostic tissue biomarker in osteosarcoma, with high levels indicating a good prognosis." (PMID 29657304, 2018). "Among those cancers, lncRNAs are more widely researched in osteosarcoma, including lncRNA-21A, UCA1, MEG3, HULC, and MIR31HG." (PMID 36057712, 2022). "On the contrary, MEG3 (maternally expressed 3) and TUS7 are downregulated in human osteosarcoma tissue." (PMID 34576322, 2021). "In retinoblastoma, HOTAIR, THOR, and MEG3 appear to have a similar influence as seen in osteosarcoma, where they also acted as oncogenes (HOTAIR and THOR) or tumor suppressors (MEG3)." (PMID 31616462, 2019). "Other than MEG3, lncRNA Highly upregulated in liver cancer (HULC) is upregulated in human osteosarcoma." (PMID 29657304, 2018). "In contrast, when compared with adjacent normal tissue, some lncRNAs—such as MEG3 and TUS7—were downregulated in human osteosarcoma tissue." (PMID 28353666, 2017). "Till now, the prognostic roles of multi-types of lncRNAs have been investigated in osteosarcoma as well, consisting of HULC, HOTTIP, MEG3, TUSC7, TUG1, 91H, and OMRUL, etc." (PMID 28415638, 2017). "When MEG3 is downregulated in the presence of EWSAT1, osteosarcoma cells grow, invade, and migrate." (PMID 37190068, 2023). "Most cancerous cell lines express MEG3 lncRNA at very low levels and so osteosarcoma cells do not have background levels of MEG3." (PMID 35741072, 2022). "Evaluated osteosarcoma cell lines showed characteristic phenotypes with unique patterns related to upregulation of MMP-7, MMP-14, BMP-7, miR-21-5p, miR-124-3p and downregulation of lncRNA MEG3." (PMID 36139691, 2022). "Furthermore, MEG3 was found to be downregulated by another lncRNA, EWSAT1, which had previously been shown to enhance cell proliferation and metastasis in both osteosarcoma and Ewing sarcoma." (PMID 31616462, 2019). "To evaluate the co-expression of imprinted genes and miRNAs at the 14q32 locus, we analyzed the expression of DLK1-DIO3 cluster genes (DIO3, DLK1, MEG3, and MEG8) and representative 14q32 miRNAs (miR-134, miR-154, and miR-382) in an independent set of 43 osteosarcoma tumor samples." (PMID 26802029, 2016). "Dysregulation of lncRNA MEG3 could act as a potential predictor of the progression and poor prognosis of osteosarcoma, and overexpression of lncRNAs UCA1 and TUG1 are essential in the poor prognosis of osteosarcoma." (PMID 31850493, 2020). "It has previously been reported that MEG3 is a tumor suppressor gene, but RTL1 and DIO3 remain candidate genes of interest and have not been well studied in osteosarcoma." (PMID 26802029, 2016).